CCZ1 (CCZ1 vacuolar protein trafficking and biogenesis associated)
Description:
Acts in concert with MON1A, as a guanine exchange factor (GEF) for RAB7, promotes the exchange of GDP to GTP, converting it from an inactive GDP-bound form into an active GTP-bound form.
Synonyms: C7orf28A; CGI-43; CCZ1A; H_DJ1163J12.2
Tractability: PROTAC: ubiquitination databases record sites on it; its protein half-life has been measured.
Gene: Protein-coding gene on chromosome 7 (5,898,692 to 5,926,550, forward strand). Ensembl gene ENSG00000122674.
Subcellular location: Lysosome membrane
Subcellular location (Human Protein Atlas): Vesicles
Pathways (Reactome):
Vesicle-mediated transport: RAB GEFs exchange GTP for GDP on RABs
Gene Ontology:
Molecular function: guanyl-nucleotide exchange factor activity; protein binding
Biological process: vacuolar transport; vesicle-mediated transport
Cellular component: late endosome; Mon1-Ccz1 complex; cytosol; lysosomal membrane
Genetic constraint (gnomAD): Loss-of-function variants: 13 observed, 30.63 expected, observed/expected ratio (o/e) 0.42, 90% interval 0.28 to 0.68. The upper end of that interval is the gene's LOEUF score, 0.68, which puts it in group 2 of 6, group 1 being the genes least tolerant of losing a copy. Missense variants: 125 observed, 234.5 expected, observed/expected ratio (o/e) 0.53, 90% interval 0.46 to 0.62. Synonymous variants: 51 observed, 68.75 expected, observed/expected ratio (o/e) 0.74, 90% interval 0.59 to 0.94.
Homologues: Orthologues: chimpanzee CCZ1B (99% identical), dog CCZ1 (96% identical), mouse Ccz1 (96% identical), macaque CCZ1 (95% identical), rat Ccz1 (91% identical), tropical clawed frog ccz1b (85% identical), zebrafish ccz1 (83% identical), Drosophila melanogaster Ccz1 (30% identical), Caenorhabditis elegans ccz-1 (28% identical). Paralogues in human: CCZ1B (100% identical).
Diseases named in the same sentence as CCZ1 in open-access papers:
CCZ1 is named in the same sentence as 18 diseases in open-access papers, as found by Europe PMC text mining. Sharing a sentence is not in itself a finding about the gene and the disease. The quoted sentences say what the papers report.
Alzheimer disease (2 papers, 2022 to 2025). A progressive, neurodegenerative disease characterized by loss of function and death of nerve cells in several areas of the brain leading to loss of cognitive function such as memory and language. "MON1A−CCZ1 dysfunction contributes to Alzheimer’s disease by impairing autophagosome maturation, while CCZ1 depletion significantly reduces SARS-CoV-2 infection, highlighting its essential role in the endosomal entry pathway." (PMID 40979223, 2025).
cervical tumors (1 paper, 2025). "In cancer, both MON1B and CCZ1 are implicated in the progression of colorectal and cervical tumors, promoting cell proliferation, migration, and invasion." (PMID 40979223, 2025).
Ebola (1 paper, 2023). "Targeting CCZ1 could potentially serve as a promising drug target for controlling infections caused by various viruses, such as SARS-CoV-2, Marburg, and Ebola." (PMID 37880247, 2023). "Thus, targeting CCZ1 could potentially serve as a promising drug target for controlling infections caused by various viruses, such as SARS-CoV-2, Marburg, and Ebola." (PMID 37880247, 2023).
myocardial infarction (1 paper, 2025). Gross necrosis of the myocardium, as a result of interruption of the blood supply to the area, as in coronary thrombosis. "Rab7a may be activated by multiple mechanisms through a GEF such as Ccz1, reducing TBC1D15 (GAP protein) levels as shown in vitro and in a mouse model of myocardial infarction, or through post-translational protein modifications." (PMID 41024170, 2025).
reovirus infection (1 paper, 2022). "In addition to WDR81 and WDR91, our screen uncovered two other proteins, Rab7 and CCZ1, that are required for endosomal maturation and reovirus infection." (PMID 35320319, 2022).
viral infection (1 paper, 2023). "More importantly, the knockout of ccz1 also lead to a dramatic drop (98.9%) in virus infection which is also mainly recovered in inverted cells." (PMID 37880247, 2023). "Notably, knockdown of CCZ1 resulted in significant reductions of viral infection (75.2% for PHH suspension MOI 1, 90.8% for PHH suspension MOI 5, 68.5% for PHH spheroid MOI 1 and 74.1% for PHH spheroid MOI 5), irrespective of infection time, as monitored by viral-specific qRT-PCR." (PMID 37880247, 2023). "Moreover, CCZ1 downregulation affects endocytosis-dependent SARS-CoV-2 infections, suggesting that CCZ1 controls a common endosomal pathway for several virus infections." (PMID 37880247, 2023).
infection (4 papers, 2022 to 2026). The state of being infected such as from the introduction of a foreign agent such as serum, vaccine, antigenic substance or organism. "CCZ1 was positively associated with infection-related, neurodegeneration-related, and proteostasis pathways, including proteasome and multiple KEGG canonical modules." (PMID 41601671, 2026). "They subsequently established CCZ1 knockout cell clones using CRISPR/Cas9 and generated vascular organoids from these clones, discovering that the infection efficiency of EBOV and MARV on CCZ1‐deficient vascular organoids was indeed reduced." (PMID 39973397, 2025). "Indeed, using multiple systems from cells to blood-vessel organoids, we were able to confirm that CCZ1 downregulation inhibits VSVΔG/MARVGP infections, trapping the virus inside early endosomal vesicles." (PMID 37880247, 2023). "While WT cells exhibited diffuse cytoplasmic staining for VSV-M protein, indicative of normal infection and viral replication, we observed only punctate anti-M immunostaining in CCZ1 mutant cells, revealing that the virus was trapped in the intracellular vesicular structures." (PMID 37880247, 2023). "Because CCZ1 is in complex with MON1 (itself formed by MON1A and MON1B), we knocked out MON1A and MON1B respectively and assessed for infection with VSVΔG/MARVGP." (PMID 37880247, 2023). "Knockout cells for CCZ1, NPC1 or RAB7 genes survived the VSVΔG/MARVGP infection and expanded over time, in contrast to GFP-expressing WT cells, confirming the role of these genes in VSVΔG/MARVGP infections." (PMID 37880247, 2023). "Deletions of NPC1, CCZ1 and RAB7 lead to a marked decrease in VSVΔG/MARVGP infection as determined by a decrease in VSV-M protein." (PMID 37880247, 2023). "Knocking-out CCZ1 and RAB7 resulted in more than 98% decrease in the relative level of infection, whereas we observed residual infection in NPC1 mutant A549 cells." (PMID 37880247, 2023). "Using these tools, we identified CCZ1, a guanine nucleotide exchange factor involved in endolysosomal trafficking, as an essential host factor for Marburg and Ebola virus infections but not infection of the Lassa arenavirus (LASV)." (PMID 37880247, 2023). "In addition, we report that CCZ1 has a role in the endosomal trafficking of endocytosis-dependent SARS-CoV-2 infections, but not in infections by Lassa virus, which enters endo-lysosomal trafficking at the late endosome stage." (PMID 37880247, 2023).
tumor (1 paper, 2024). "Our analysis demonstrated that CCZ1 was overexpressed in CSCC tumor tissues and was an independent prognostic risk factor affecting the overall survival (OS) of CSCC patients." (PMID 39062041, 2024). "Immunohistochemical analysis of clinical specimens revealed significantly greater CCZ1 protein expression in CSCC tumor tissues compared to normal cervical tissues." (PMID 39062041, 2024). "Our findings revealed a notable increase in CCZ1 expression in tumor tissues compared to normal tissues in CHOL (p < 0.05), GBM (p < 0.05), PAAD (p < 0.05), THYM (p < 0.05), KIRP (p < 0.05), and DLBC (p < 0.05) patients." (PMID 39062041, 2024). "Correlation analysis revealed a positive association between CCZ1 expression and the expression of immunogenic cell death modulators, which indicates that CCZ1 is involved in the regulation of immune responses within the tumor microenvironment." (PMID 39062041, 2024). "To enhance clinical applicability, we developed and validated a nomogram that integrated CCZ1 expression with age, stage, and tumor grade." (PMID 39062041, 2024). "We investigated the expression levels of CCZ1 mRNA in other tumor types." (PMID 39062041, 2024). "Our findings revealed a mechanistic link between CCZ1 and MMPs, particularly MMP2 and MMP17, which are known regulators of tumor invasion and metastasis." (PMID 39062041, 2024).
CCZ1 also shares sentences with these, for which no sentence is quoted: bacterial infection (1 paper); cancer (1); cervical cancer (1); cervical squamous cell carcinoma (1); cognitive decline (1); hemorrhagic fever (1); Hermansky-Pudlak syndrome (1); infectious disease (1); Niemann-Pick disease (1); Parkinson disease (1).